EPHA2 (EPH receptor A2)
Diseases named in the same sentence as EPHA2 in open-access papers (continued):
Sharing a sentence is not in itself a finding about the gene and the disease.
tumor (continued). "Loss of EphA2 reduced the proliferation of erlotinib-resistant tumor cells with the EGFR (T790M) mutation in vitro and in vivo, in TKI-resistant EGFR L858R+790M transgenic mice." (PMID 33572284, 2021). "EPHA2 transcript levels were elevated in human breast‐to‐bone metastases, and EphA2 loss of function in tumor cells reduced tumor‐induced osteolysis in two independent models in vivo." (PMID 33869989, 2021). "In this study, we identified EphA2 (Eph type-A receptor 2)-associated super-enhancer EphA2-SE, which exists in five tumor cells in four super-enhancer databases." (PMID 33712565, 2021). "EPHA2 expression has been shown positively associated with tumor size and Fuhrman nuclear grade in KIRC57 and promoting resistance to chemotherapy of sunitinib." (PMID 34319007, 2021). "EphA2 was expressed in cancer cells primarily on the cell membrane, but was also observed in tumor-associated blood vessels." (PMID 33092175, 2020). "EphA2 was found to be expressed in tumor cells and/or tumor-associated blood vessels in both primary and metastatic lesions with a concordance rate of approximately 90%." (PMID 33092175, 2020). "All samples that had EphA2-positive tumor-associated blood vessels showed also EphA2 expression in ≥10% of cancer cells." (PMID 33092175, 2020). "Frequently overexpressed in OC, EphA2 associates with high tumor grade, advanced stage, and poor clinical outcome." (PMID 32115889, 2020). "Among the Eph receptor family members, EphA2 and EphA3 have been identified as tumor-associated antigens (TAAs), and their epitopes can be recognized by both CD4+ and CD8+ T cells." (PMID 33288738, 2020). "EphA2 was detected in ≥10% of cancer cells (EphA2-positive) in 19 of 20 samples (95%), and was detected in tumor-associated blood vessels in approximately 80% of the samples." (PMID 33092175, 2020). "Vascular-associated genes such as VE-cadherin and EphA2 are involved in the ability of aggressive tumor cells to form VM." (PMID 31936664, 2020). "To define the signaling pathways that differ between CARs with CD28.ζ (CD28-CAR), 41BB.ζ (41BB-CAR), and MyD88.CD40.ζ (MC-CAR), we generated CARs specific for EphA2, a tumor-associated antigen broadly expressed in brain and solid tumors." (PMID 33148882, 2020). "The application of 17-DMAG induced the degradation of EphA2 with a subsequent presentation of the tyrosine kinase receptor genes to EphA2-specific CD8+ T lymphocytes which caused protective anti-tumor immunity." (PMID 31652993, 2019). "Despite the clinical and pathological importance of tumour-associated vasculature, the underlying mechanism involving EphA2 is poorly known." (PMID 30914876, 2018). "EphA2 is highly correlated with the formation of many solid tumors and has been linked to the dysregulation of signaling pathways that promote tumor cell proliferation, migration, and invasion as well as angiogenesis." (PMID 30451837, 2018). "Interaction between EphA2 and Ephrin A1, along with other guidance molecules, will navigate developmental guidance that causes sheets of cell layers to become tumours." (PMID 30914876, 2018). "Our previous studies demonstrated that EphA2 plays a key role in signal transduction pathways associated with the regulation of growth, proliferation, and metastasis of tumor cells." (PMID 28624791, 2017). "Blocking the activation of EphA2 not only prevents tumors from progressing but also increases the susceptibility of tumor cells to chemotherapy." (PMID 28624791, 2017). "FCS measurements were performed on live cancer cells with stable expression of GFP-tagged EphA2 mutation constructs (DU145), and mouse epithelial tumor cells with EphA1/EphA2 gene knockout and stable expression of GFP-tagged EphA2 mutation constructs." (PMID 28338017, 2017). "In univariate analyses, CEACAM1, CEACAM5 and CEACAM6 expression showed significant association with primary tumor site, while EPHA2 expression was associated with both lymphatic and venous invasion." (PMID 29262644, 2017).
tumor (continued). "Multiple publications have shown that EphA2 overexpression is strongly correlated with tumor progression; consequently, high EphA2 levels are associated with worse patient survival." (PMID 28165374, 2017). "EphA2 overexpression on tumor cells is associated with modulation of signal transduction pathways involved in cytoskeletal modulation, cell adhesion, migration, metastasis, proliferation, and angiogenesis." (PMID 28686661, 2017). "Our results decipher the mechanism through which HIC1 deficiency induce ESCC cells to undergo EMT and promote tumor progression and metastasis through activation of EphA2 signaling pathway." (PMID 26510908, 2015). "Other members of the Eph receptor and ephrin families, including EphA2, EphB4, ephrin A1, and ephrin A3, have previously been implicated in radioresistance in different tumor models." (PMID 25879388, 2015). "This is because EphA2 is overexpressed in many tumors, including tumor stem cells, and functionally associated with tumor progression." (PMID 24760010, 2014). "Activation by interaction with ephrin-A1 causes phosphorylation of EphA2 that generates an anti-oncogenic signal as shown by the observation that forced activation by exposure to soluble ephrin-A1 can inhibit tumor growth both in vitro and in vivo." (PMID 25344320, 2014). "An over-expression of EPHA2 has been observed in several tumor entities, which in turn was often linked to more aggressive tumor features and/or worse prognosis." (PMID 25025847, 2014). "A positive EPHA1 and EPHA2 protein staining as well as a low EFNA1 protein level were significantly linked to more aggressive tumor features, but only a positive EPHA1 immunoreactivity was significantly associated with poor survival." (PMID 25025847, 2014). "In this study, we attempted to understand the underlying mechanisms by which EphA2 over expression leads to enhanced or irregular claudin-2 expression via cdx-2 modulation and promote tumor growth in NSCLC cells." (PMID 22824143, 2012). "A definitive role for EphA2 in malignancy is illustrated by diminished tumor growth, angiogenesis, and metastasis in EphA2 deficient mice." (PMID 20628489, 2010). "EphA2 was observed in tumor-associated vascular endothelial cells, ephrinA1 was detected in tumor and endothelial cells, and soluble EhpA2-Fc exhibits anti-angiogenic and anti-tumor effects, suggesting their involvement in tumor angiogenesis." (PMID 20687922, 2010). "EphA2 role in tumorigenesis seems to concern invasion and angiogenesis process; in fact, levels of this receptor in endothelial and tumoral cells are linked to a major density of micro vessels and to an high expression of MMP-9, MMP-2, MT1-MMP." (PMID 19949545, 2009). "Intriguingly, EPHA2 has been implicated in tumor angiogenesis and neurite outgrowth; however, little is known about its role in the development and homeostasis of the avascular, noninnervated lens." (PMID 19005574, 2008). "It would also be intriguing to delineate molecular mechanisms underlying the antigen presentation against EphA2- and IL-13Rα 2-derived epitopes in the patient AA-1 that led to anti-tumor immunity instead of tolerance." (PMID 18093336, 2007). "EphA2 role in tumorigenesis seems to concern invasion and angiogenesis process; in fact, levels of this receptor in endothelial and tumoural cells are linked to a major density of micro vessels and to an high expression of MMP-9, MMP-2, MT1-MMP." (PMID 19384429, 2007). "We evaluated expression of IL-13Rα2 and EphA2 in tumor tissues derived from the patient AA-1, as these GAAs encode well characterized HLA-A2-restricted CTL epitopes." (PMID 18093336, 2007). "VEGF has been implicated to be a major mediator of tumor-angiogenesis, and EphA2-blockade has been shown to inhibit VEGF-induced angiogenesis." (PMID 15563374, 2004).
tumor (continued). "Moreover, drug-resistant tumor cell-derived small EVs have also been found to be enriched in EphA2 and linked to the induction of a higher invasive capability of recipient sensitive BC cells." (PMID 40691627, 2025). "This investigation evaluates the potential therapeutic application of a bispecific antibody (BsAb), which simultaneously targets EphA2, a tumor-associated antigen, and CD11b, a protein expressed by tumor-associated macrophages and myeloid-derived suppressor cells (TAMCs)." (PMID 40434019, 2025). "Additionally, EphA2 expression was linked to perineural dissemination in AdCC, suggesting its potential as a therapeutic target in managing this tumor." (PMID 40421081, 2025). "EphA2 expression is linked to the higher vascular mimicry noted in PAK4KO tumours." (PMID 41294859, 2025). "Although EphA2 signaling is generally associated with tumor-suppressive effects, its activation in this context may paradoxically promote angiogenesis via VEGF-A and TNF, likely influenced by high ephrin-A1 expression in endothelial cells." (PMID 41200151, 2025). "Elevated expression of EphA2 in BCA is associated with tumor progression and an adverse prognosis." (PMID 38612592, 2024). "Notably, removing EPHA2+ cells from mouse ESC-derived hepatic lineage reduced tumor formation after transplanting them into immune-deficient mice." (PMID 38811016, 2024). "Indeed, in advanced stages of CRC, where the microenvironment is more sophisticated and complex, EphA2 has been associated with tumor progression." (PMID 38651144, 2024). "EPHA2 overexpression is associated with tumor progression, metastasis and prognosis of HCC." (PMID 36744264, 2023). "Interestingly, EPHA2 immunohistochemical expression was associated with tumor vertical thickness and marginally with the presence of metastasis, both parameters indicating an aggressive clinical behavior." (PMID 35626181, 2022). "EPHA2 has also been speculated to influence tumor cell lysis and contribute to susceptibility to Vδ1 γδ T cells’ cytotoxic reactivity." (PMID 35328669, 2022). "High levels of EPHA2 protein expression have been associated with a higher tumor grade, advanced disease stage, high MVD, strong stromal reaction and epithelial matrix metalloproteinase (MMP)-9, epithelial MMP-2, and epithelial membrane-type 1 MMP expression, as well as shorter patient survival." (PMID 35328669, 2022). "Referring to these reports, we assumed that anlotinib suppresses radioresistance and tumor angiogenesis of EC cells through inhibiting EphA2, and it may renew the mechanism underlying radioresistance in EC and provide for therapeutic reference." (PMID 36090890, 2022). "EphA2 upregulation is associated with tumor invasion, metastasis, survival, and angiogenesis." (PMID 33685469, 2021). "We postulated that by engineering the virus to encoding a tumor-associated shared antigen, we could bypass viral host EphA2 transcriptional downregulation and improve immune recognition of that shared antigen during tumor infection." (PMID 34599026, 2021). "Our previous studies found that EphA2 is highly expressed in tumor‐associated vascular endothelium." (PMID 33869989, 2021). "Although EphA2 loss of function impairs osteolysis, it is unclear if this effect is mediated by direct effects on osteoclast progenitors or indirectly through effects on other cell types, including tumor cells or other components of the bone microenvironment." (PMID 33869989, 2021). "Expression of both proteins was correlated with increased TNM stage and LN metastasis rate, with EPHA2 overexpression also linked to deeper levels of tumor invasion and found to be an independent poor prognostic factor, as its increased expression correlated with decreased OS." (PMID 34445116, 2021). "Notably, consistent with our observations, it was previously demonstrated that the loss of EphA2 in APC min/J mice led to a reduction of 33% of the tumor multiplicity in the small intestine and of the 60% and in the large intestine." (PMID 32316101, 2020).
tumor (continued). "In addition, EphA2 expression has associations with poor prognosis, elevated metastatic potential, and reduced survival of tumor patients." (PMID 32811512, 2020). "Moreover, high expression of EphA2 in the endothelial lining of tumour-associated vasculature in other tumour types has also been documented, including breast cancer and Kaposi’s sarcoma." (PMID 30914876, 2018). "Stimulation of EphA2 causes powerful changes in a tumour cell’s behaviour." (PMID 30914876, 2018). "In the case of GBM, overexpression of EphA2 is linked to low survival rate and tumour recurrence." (PMID 30914876, 2018). "However, regulation of EphA2 is complex, and several factors, including ligand binding and downstream events, can cause EphA2 to act as a tumor suppressor or as an oncogenic protein." (PMID 30222105, 2018). "Interestingly, knockout of ITGA5 did not influence growth or metastasis of PDAC, indicating that RCP's ability to traffic EphA2 is more closely associated with tumour dissemination than is the trafficking of its integrin cargo in tumour cells." (PMID 28294115, 2017). "Overexpression of EphA2 is associated with tumour progression or poor patient survival." (PMID 23738943, 2013). "Moreover, EphA2 deletion mice show increased susceptibility to carcinogen-induced skin tumorigenesis." (PMID 22916121, 2012). "Although it remains unclear how this pathway mechanistically translates to angiogenic potential, AKT is a known mediator of angiogenic processes and AKT-mediated EphA2 phosphorylation within GBM-associated tumor vasculature increases with malignancy." (PMID 20628489, 2010). "Furthermore, EphA2 is commonly detected in the tumor associated vasculature, where it facilitates angiogenesis." (PMID 20628489, 2010). "Furthermore, we found that the PLEKHA1-TACC2 fusion proteins could significantly promote tumor growth by inducing VM formation, which is caused by stabilizing EphA2 protein and upregulating the EphA2/AKT/MMP2 signaling pathway." (PMID 40615663, 2025). "OPCML exerts its tumor suppressor effect by inhibiting several cancer hallmark phenotypes in vitro, and abrogating tumorigenesis in vivo, by downregulating/inactivating a specific spectrum of Receptor Tyrosine Kinases (RTKs), including EphA2, FGFR1, FGFR3, HER2, HER4, and AXL." (PMID 36835855, 2023). "In addition, EPHA2 was positively associated with a plethora of adverse clinical characteristics, such as high disease stage, high tumor grade, increased depth of myometrial invasion, low estrogen and progesterone receptors expression, high Ki67 index, and shorter OS." (PMID 34445116, 2021). "Thus, ephrin A1-associated tumor suppression might result from EphA2 downregulation as well as direct signaling through EphA2." (PMID 32811512, 2020). "Moreover, loss of EPHA2 reduced tumor formation in Apc Min/+ mice." (PMID 25193853, 2014). "Erythropoietin-producing hepatocellular receptor A2 (EphA2) has emerged as a key mediator that promotes tumor malignant progression." (PMID 41977404, 2026). "In vivo, EphA2-CAR T cells demonstrated superior tumor control and improved survival compared to B7-H3-CAR T cells in 2 of 3 orthotopic G3MB models." (PMID 41756431, 2026). "Using an orthotopic and immunocompetent mouse model, EphA2 knockdown resulted in significantly reduced tumor wet weight and increased tumor cell apoptosis compared to those in the control group in the orthotopic RCC mouse model." (PMID 41440001, 2025). "EphA2-79 CAR-T cells showed a continuous decrease in tumor size after 11 days, and with the tumor disappearing entirely by the end of the test." (PMID 40181964, 2025). "EPHA2 was identified in frozen tissue by real-time reverse transcriptase polymerase chain reaction, with higher mRNA expression in tumor tissue than in normal salivary glands." (PMID 40421081, 2025). "The Δ Ecto and EphA2-85 CAR-T cell groups separated the tumor, which was confirmed using a photograph." (PMID 40181964, 2025).
tumor (continued). "To elucidate the mechanism by which tumor-specific EphA2 suppresses CD8+ T-cell activation, we performed gene expression profiling of dissected lung tumors using NanoString’s Mouse PanCancer Immune Profiling Panel." (PMID 40867322, 2025). "Numerous studies have highlighted EphA2's role in tumour cell proliferation, migration and survival, making it a prime candidate for targeted therapy in solid tumours." (PMID 39763064, 2025). "Research revealed that a tandem configuration of IL13 and EphA2 scFv demonstrated that the IL13-anti-EphA2 TanCAR showed significantly enhanced anti-tumor efficacy compared to single CAR-T cells, in both in vitro and in vivo settings." (PMID 40861448, 2025). "We engineered CAR-T cells targeting tumor-specific EphA2 antigens and confirmed that the tumor-killing activity and pro-inflammatory cytokine production in A549 cells were significantly higher than those in normal T cells." (PMID 40181964, 2025). "To investigate the clinical significance of USP5/EphA2 axis, we used IHC to detect expression levels of USP5 and EphA2 in 119 tumor tissues from patients with NPC, who received radical radiotherapy and concurrent chemotherapy according to a uniform guideline." (PMID 39897046, 2025). "Ultimately, the effect of EphA2 in the tumor dampens the anti-tumor immune response and perpetuates the vicious cycle of tumor immune escape and growth." (PMID 40867322, 2025). "Overall, this suggests tumor-specific EphA2 modulates the quality of tumor immune infiltrate, which then subsequently impacts tumor growth." (PMID 40867322, 2025). "Our work aligns with the emerging literature that reveals EphA2’s role in immune-mediated mechanisms, in addition to its well-studied tumor-intrinsic mechanisms, that promote cancer progression in multiple tumor types." (PMID 40867322, 2025). "In SGC, EphA2 and ephrinA1 markers have been associated with MVD, indicating a critical role in tumor angiogenesis." (PMID 40421081, 2025). "Using their 283LM model, they show increased T-cell tumor infiltration and activity and reduced MDSCs in EphA2 KO tumors." (PMID 40867322, 2025). "In summary, gene expression analysis provided evidence that tumor-specific EphA2 increases the levels of myeloid chemoattractants, monocyte/macrophage lineage cells, and immunosuppressive proteins." (PMID 40867322, 2025). "EphA2 facilitates malignant progression by mediating interactions between tumor cells and their microenvironment, including endothelial and immune cells, and is associated with poor clinical prognosis, particularly in non-small cell lung cancer (NSCLC)." (PMID 40181964, 2025). "To confirm the database mining results, we further analyzed PDAC samples in a TMA by IHC analysis and found that more than 95% of tumor samples stained for membranous EphA2 expression." (PMID 40225586, 2025). "The small-molecule inhibitor GLPG1790 blocks EphA2 phosphorylation at Tyr588 and Ser897, modulates differentiation markers, and reduces tumor growth, showing synergy with standard therapies." (PMID 41200151, 2025). "In summary, our investigations suggest EphA2 overexpression leads to decreased anti-tumor immunity by increasing the recruitment of suppressive myeloid populations and decreasing T-cell infiltration and activation in NSCLC." (PMID 40867322, 2025). "In a separate OS model using MG63 cells (s.c. inoculated) and PB‐derived EphA2‐CAR‐NK cells for treatment, primary tumour growth was markedly inhibited in the EphA2‐CAR‐NK cell group, accompanied by a notable survival benefit." (PMID 39763064, 2025). "The tumor weight in the EphA2-knockdown group was significantly lower than that in the control group (average tumor wet weight: 636.5 ± 288.9 vs. 1569.9 ± 595.5 mg; p = 0.009)." (PMID 41440001, 2025). "Together, these studies suggest that tumor-intrinsic EphA2 recruits monocytes and promotes their transformation into TAMs, which inhibit the activation of anti-tumor T cells." (PMID 40867322, 2025).